CXCL16 (C-X-C motif chemokine ligand 16)
Diseases named in the same sentence as CXCL16 in open-access papers (continued):
Sharing a sentence is not in itself a finding about the gene and the disease.
melanoma (16 papers, 2009 to 2025). A malignant, usually aggressive tumor composed of atypical, neoplastic melanocytes. "CXCR6 also positions tumor reactive CD8+ TRM with CXCL16+ DC clusters in the skin of melanoma-associated vitiligo, which favor their persistence." (PMID 36311728, 2022). "Cxcr6- deficient mice or CXCL16 neutralizing Ab resulted in an enhanced metastasis to the liver by B16 melanoma cells or Lewis Lung tumor cells." (PMID 36311728, 2022). "Moreover, our data suggest that the enhanced melanoma colonization seen in Mcpt4/Mcpt6/Cpa3-deficient animals is associated with a defective CXCL16/CD1d/iNKT cell axis." (PMID 28212574, 2017). "Furthermore, we stimulated LOX melanoma cells stably expressing a CXCL16 variant that lacks the cytoplasmic tail due to truncation (LOX-ΔCXCL16) with recombinant and membrane expressed CXCR6, as well as control membrane fractions and did not observe any ERK1/2 phosphorylation either." (PMID 28698473, 2017). "Exposure to melanoma-conditioned medium induced the upregulation of bFGF, CXCL-16, TIMP-2, and E-cadherin in NHKs, alongside downregulating TGF-β and MMP-9." (PMID 40869222, 2025). "Other murine melanoma models showed tumor DCs presenting CXCL16 and trans-presenting IL-15 to incoming T cells in the TME, while blocking these signals led to declines in their survival." (PMID 40862776, 2025). "This reverse signaling depends on the intracellular domain of CXCL16 and promotes migration in CXCL16-expressing melanoma and glioblastoma cells in vitro." (PMID 28698473, 2017). "Together, these findings indicate a protective role of mast cell-specific proteases in melanoma dissemination, and suggest that this effect involves a CXCL16/CD1d/NKT cell axis." (PMID 28212574, 2017). "In the next step, we stimulated stably CXCL16 expressing LOX melanoma cells (LOX-CXCL16) with recombinant CXCR6 and observed again an activation of ERK1/2 (upper part)." (PMID 28698473, 2017). "Expression of CXCR6 and CXCL16, comprising another significant chemokine axis, is evaluated in several cancers, such as renal, rectal, pancreatic ductal adenocarcinoma, nasopharyngeal carcinoma, and melanoma." (PMID 34298782, 2021). "Hence, a plausible scenario is that the impaired ability of multiple KO mice to combat melanoma is due to effects on cell populations that are dependent on CXCL16." (PMID 28212574, 2017). "Since potent IFNγ production is associated with enhanced antitumor responses, we examined whether CXCL16 co-stimulation of iNKT cells during glycolipid activation modified tumor clearance in an experimental model of B16-F10 melanoma metastasis to the liver." (PMID 27471636, 2016). "The comparison of data obtained with NHKs, NHFs, and CAFs exposed to melanoma-derived SPNs evidenced bFGF, CXCL-16, and TIMP-2 as common features, suggesting a crucial role for melanoma biology." (PMID 40869222, 2025). "Consistently, elevated expression of CXCL-16 and its receptor, CXCR6, has emerged as a strong predictor of overall survival in melanoma patients." (PMID 40869222, 2025). "In mouse melanoma models, CD11c+ dendritic cells (DCs) were found to closely cluster with CXCR6+ TRMs around hair follicles, express high CXCL16, and were required to maintain TRM cell populations." (PMID 40862776, 2025). "The CXCR6/CXCL16 axis is pro‐inflammatory, CXCR6 is expressed by a self‐renewing subset of melanoma stem cells, and melanoma secretes CXCL16, contributing to CXCR6‐mediated leukocyte recruitment." (PMID 34129290, 2021). "Notably, melanoma cells in dynamic interaction with NHKs exhibited a significant downregulation of bFGF, CXCL-1, CXCL-16, and IL-8 compared to monocultures, possibly since keratinocytes are a primary source of these factors." (PMID 40869222, 2025). "CXCL-16 promotes melanoma cell migration but does not affect proliferation or resistance to apoptosis." (PMID 40869222, 2025). "Chemokine CXCL16 and its T cell ligand CXCR6 are also key propagators of melanoma." (PMID 34129290, 2021).
melanoma (continued). "We now observed that reverse signaling via the transmembrane chemokine CXCL16 promotes migration in the tumor context, but does not affect proliferation or rescue from apoptosis in melanoma or glioblastoma cells." (PMID 28698473, 2017). "We showed that reverse signaling via CXCL16 promotes migration in CXCL16-expressing melanoma and glioblastoma cells, but does not affect proliferation or protection from chemically-induced apoptosis." (PMID 28698473, 2017). "In this study, we describe perifollicular and interfollicular clustering of mouse and human skin CD8 TRM cells in response to melanoma, respectively, and show that persistent clustering with DCs is required for skin TRM cell maintenance and dependent on the interaction between CXCR6 and CXCL16." (PMID 34362825, 2021). "However, in these CXCL16-transfected melanoma cells, we did not observe any regulation of proliferation upon stimulation with recombinant CXCR6, nor could we detect less cleavage of poly(ADP ribose) polymerase (PARP) after induction of apoptosis with 0.1 μg/mL camptothecin." (PMID 28698473, 2017). "The specificity of reverse signaling was proven by silencing experiments, as well as by transfection experiments using a CXCL16-negative, CXCR6-negative melanoma cell line to investigate intracellular signaling and biological effects upon stimulation with CXCR6." (PMID 28698473, 2017). "LOX melanoma cells do not endogenously express CXCL16, nor CXCR6, and so, we generated LOX clones expressing transmembrane CXCL16 (LOX-CXCL16) or a C–terminally truncated version of transmembrane CXCL16 (LOX-ΔCXCL16) and a clone from the empty expression vector (LOX-pcDNA)." (PMID 28698473, 2017).
ovarian cancer (16 papers, 2009 to 2025). A primary or metastatic malignant neoplasm involving the ovary. "Tumor-promotive tumor-associated macrophages (TAMs) and the CXCL16/CXCR6 axis have been reported to be correlated with the limited efficacy of chemotherapy in ovarian cancer (OC)." (PMID 37272931, 2023). "The correlation analysis indicated a positive association of CXCL16 expression with an activation of macrophages in ovarian cancer." (PMID 36686729, 2022). "Researchers also found that upregulated CXCL14 and CXCL16 were associated with poor survival outcomes and promoted ovarian cancer cells proliferation." (PMID 33763130, 2021). "Macrophage-derived CXCL16 promoted migration and invasion of ovarian cancer SCOV3 cells by enhancing the activity of the PI3K/Akt pathway." (PMID 36686729, 2022). "Human ovarian cancer tissue significantly increased expression of CXCL16 in comparison with both corresponding adjacent and para-cancerous tissues." (PMID 36686729, 2022). "Soluble CXCL16 has been shown to increase the invasiveness of pancreatic cancer cells and ovarian cancer." (PMID 35052825, 2022). "Macrophages promote the migration and invasion of ovarian cancer by binding to its unique ligand CXCL16 to activate PI3K/Akt signaling pathway." (PMID 33829065, 2021). "These cells increase the expression of CXCL16, which then aids in the implantation of ovarian cancer cells and the formation of peritoneal metastasis." (PMID 33800554, 2021). "More importantly, the expression of CXCL16 and CXCR6 had been implied to be overexpressed in epithelial ovarian cancer which was closely associated with tumor growth, proliferation, invasion and lymph node metastases." (PMID 30996686, 2019). "We found high expression levels of CXCL16 in cancers of the ovary, breast, prostate, colon and liver – all cancers described as arising in the context of inflammation." (PMID 19690611, 2009). "The overexpression of STK3 can promote ovarian cancer cells to secrete CXCL16 and CX3CL1." (PMID 33062724, 2020). "Indeed, inhibition of ADAM10/17-mediated CXCL16 shedding reduced the migrating potential of ovarian cancer cells." (PMID 27471636, 2016). "Our results showed that CXCL1, CXCL8, CXCL9, CXCL11, CXCL12, CXCL16, and CXCL17 were remarkably elevated in ovarian cancer compared to those in normal tissue." (PMID 33763130, 2021). "We also found that STK3 promoted the recruitment of CD8+ T-cells via an increase in chemokine CXCL16 and CX3CL1 production in human ovarian cancer cells." (PMID 33062724, 2020). "In bladder cancer, ovarian cancer, and papillary thyroid cancer, the level of CXCL16 expression is not related to the patient’s overall survival." (PMID 33800554, 2021). "Meanwhile, the chemokine landscape of ovarian cancer was found to be quite heterogeneous, because of different functions of known lymphocyte-recruiting chemokines in TME, such as CCL2, CXCL9, CXCL10, CXCL12, and CXCL16." (PMID 34386037, 2021). "It was also found that a reduced expression of CD44, Nanog, Oct4, CXCL16 and EGFR after ST6GALNAC1 silencing in OCSCs indicated that CD90+ stem cells infected with miRNA against ST6GALNAC1 had weaker self-renewal capacity in ovarian cancer." (PMID 30996686, 2019). "In ovarian cancer, CXCR6 is highly expressed on TRM‐like cells, and its ligand CXCL16, primarily produced by EpCAM−CD45− stromal cells, facilitates their spatial retention within the tumor microenvironment, suggesting that CXCL16 delivery or CXCR6 engineering may promote TRM accumulation." (PMID 41361844, 2025).
renal fibrosis (16 papers, 2012 to 2025). A final common manifestation of a wide variety of chronic kidney diseases characterized by glomerulosclerosis and tubulointerstitial fibrosis. "In a mouse model of renal fibrosis it was demonstrated that CXCL16 gene expression was induced in the kidney and that CXCL16 plays a pivotal role in the pathogenesis of renal fibrosis." (PMID 33552057, 2020). "Targeted disruption of CXCL16 prevented the development of renal fibrosis by suppressing the recruitment of CXCR6-expressing bone marrow-derived fibroblast precursors, macrophages and T cells into the kidney and myofibroblast formation." (PMID 33552057, 2020). "Previous report has demonstrated that CXCL16 involves in the pathogenesis of renal fibrosis and injury." (PMID 31379980, 2019). "CXCL16 is induced in kidney tubular epithelial cells in vivo in a murine model of renal fibrosis induced by obstructive injury." (PMID 26941655, 2016). "We have recently studied the functional role of CXCL16 in the pathogenesis of renal fibrosis in a murine model of obstructive nephropathy using CXCL16 knockout mice." (PMID 26941655, 2016). "Our previous studies have shown that CXCL16 is upregulated in the kidney following unilateral ureteral obstruction and angiotensin-induced renal injury, and genetic disruption of CXCL16 attenuates renal fibrosis and preserves kidney function." (PMID 27191747, 2016). "We have recently shown that CXCL16 is induced in tubular epithelial cells in response to obstructive injury and targeted disruption of CXCL16 inhibits the recruitment of bone marrow-derived fibroblasts into the kidney and the development of renal fibrosis." (PMID 24130892, 2013). "The critical role of IL-34 and CXCL16 in renal fibrosis was established by previous studies." (PMID 40131554, 2025). "Previous studies established the key role of IL-34 and CXCL16 in renal fibrosis." (PMID 38152332, 2023). "Cxcl16 plays a crucial role in the accumulation of myeloid fibroblasts during renal fibrosis." (PMID 26285014, 2015). "Our recent study provides evidence that accumulation of myeloid fibroblast precursors in the kidney and development of renal fibrosis required chemokine CXCL16 induction in the renal tubular epithelial cells in a murine model of renal fibrosis induced by unilateral ureteral obstruction." (PMID 23272241, 2012). "Moreover, CXCL16/CXCR6 has contributed to the pathogenesis of renal fibrosis." (PMID 31379980, 2019). "Intestinal ILC3s migrate to the kidney through CXCL16/CXCR6 axis and IL‐17A derived from ILC3s in PD‐1‐dependent manner promotes renal fibrosis." (PMID 40801800, 2025). "A previous study demonstrated that the CXCL16 signaling pathway contributes to the renal injury in diabetic nephropathy mouse model and CXCR6 regulates the collagen deposition and expression of collagen I and fibronectin through recruitment of bone marrow derived fibroblast in renal fibrosis." (PMID 33922243, 2021).
pancreatic cancer (14 papers, 2021 to 2025). "In pancreatic cancer, the aberrant homotrimeric variant of Col1 produced by tumor cells exhibits oncogenic properties by downregulating the expression of CXCL16, significantly inhibiting the infiltration and activation of T cells, particularly CD8+ T cells." (PMID 39845977, 2024). "The results showed that CXCL5 expression in pancreatic cancer was higher than that in other tumours, whereas in pancreatic cancer, CXCL16 expression was the highest." (PMID 35468838, 2022). "Furin, an endoprotease expressed on the surface of pancreatic cancer cells, cleaves CXCL16, thus promoting NK cell infiltration via the ERK signaling cascade." (PMID 34970253, 2021). "The NK cell-recruiting protein-conjugated antibody (NRP-body) with a cleavable CXCL16 molecule was used in another study to increase NK cell trafficking and penetration into pancreatic tumors." (PMID 34970253, 2021). "Other examples include T cells engineered to express the chemokine receptor CXCR5 to improve migration in CXCL13 rich lung as well as head and neck cancer microenvironments, and CXCR6 expression that improved migration and function in hypoxic CXCL16-rich pancreatic tumor milieus." (PMID 41181132, 2025). "The furin domain could be cleaved by furin expressed on the surface of pancreatic cancer cells, thus creating a CXCL16 gradient." (PMID 38339310, 2024). "Overexpression of CXCL16 can promote KRAS-induced pancreatic tumor growth." (PMID 35957897, 2022). "The data showed that most of chemokines, such as CX3CL1, CXCL16, CXCL3, CXCL9, and CXCL5, were significantly high expressed in pancreatic tumor tissues compared to normal tissues." (PMID 35478937, 2022). "Other members of the C-X-C motif chemokine family were found to be upregulated in pancreatic cancer cells after Rintatolimod treatment, like CXCL 1, CXCL2, CXCL3, CXCL8 (IL-8), CXCL11, CXCL14, and CXCL16." (PMID 34207861, 2021).
rheumatoid arthritis (13 papers, 2009 to 2025). A chronic, systemic autoimmune disorder characterized by inflammation in the synovial membranes and articular surfaces. "Studies have demonstrated a strong association between CXCL16 levels and the severity, disease activity, and prognosis of conditions such as multiple sclerosis, autoimmune hepatitis, rheumatoid arthritis, Crohn's disease, and psoriasis." (PMID 41357074, 2025). "A recent study has demonstrated that upregulation of serum CXCL16 levels in patients with rheumatoid arthritis-associated pulmonary fibrosis stimulates proliferation, migration, and collagen production of fibroblasts via the PI3K/AKT/FOXO3a pathway." (PMID 38789926, 2024). "Recent studies suggest the contribution of CXCL16 in the pathogenesis of autoimmune diseases such as Crohn’s disease, multiple sclerosis, rheumatoid arthritis, and lupus." (PMID 40806424, 2025). "CXCR6/CXCL16 is highly expressed in the synovial tissue of rheumatoid arthritis (RA) patients, where it recruits T cells and monocytes to the inflamed joints, promoting the production of pro‐inflammatory cytokines that exacerbate joint inflammation and damage." (PMID 41291399, 2025). "In a murine rheumatoid arthritis model, CXCL16/CXCR6 signaling has been reported to have a central role in endothelial progenitor cell chemotaxis and angiogenesis." (PMID 31527616, 2019). "It has been shown that CXCL16 is an important mediator of angiogenesis in rheumatoid arthritis." (PMID 33552057, 2020). "A study compared OA and rheumatoid arthritis (RA) patients and indicated that CXCL16 and RANKL expressions were lower in patients with OA than that in patients with RA." (PMID 37013568, 2023). "Moreover, CXCL16 also mediates the activity of STAT3 in rheumatoid arthritis synovial fibroblasts." (PMID 31379980, 2019). "Similar to rheumatoid arthritis, in arthritis-irAE, SF T cells highly expressed CXCR3 and CXCR6, and their matching ligands, CXCL9/10/11, and CXCL16 were mainly produced by myeloid cells." (PMID 35413951, 2022). "Our findings are in agreement with previous reports that demonstrated CX3CL1, but not CXCL16 induction by TNF-α in rheumatoid arthritis synovial tissue fibroblasts." (PMID 33552057, 2020). "CXCL16 has been shown to be involved in the recruitment of T cells to inflamed liver and the joints of patients with rheumatoid arthritis, but there has been no reports suggesting CXCL16 expression in these organs in the absence of inflammation." (PMID 19415545, 2009). "Additionally, IL-1β treatment did not upregulate the production of CXCL16 by rheumatoid arthritis synovial tissue fibroblasts." (PMID 33552057, 2020). "Despite being ELR negative, CXCL16 has been shown to be an angiogenic factor for recruitment of human umbilical vein endothelial cells and an important mediator of angiogenesis in rheumatoid arthritis." (PMID 26021984, 2015). "In contrast, stimulation of rheumatoid arthritis synovial tissue fibroblasts, bronchial epithelial cells, smooth mushle cells, umbilical vein endothelial cells and annulus fibrosus cells by TNF-α did not influence CXCL16 expression." (PMID 33552057, 2020).
gastric cancer (12 papers, 2015 to 2025). A primary or metastatic malignant neoplasm involving the stomach. "On the other hand, in gastric cancer, migration is associated with CXCL16 activation of STAT3, which leads to an increase in Ror1 receptor tyrosine kinase expression." (PMID 33800554, 2021). "Whereas in gastric carcinomas, lower expression of CXCL16 in the tumor is associated with lymphatic invasion, and in renal cell carcinoma with the tumor stage." (PMID 33800554, 2021). "Meanwhile, a recent study demonstrated that the activation of Wnt/Ror2 signaling in mesenchymal stem cells promotes cell proliferation of gastric cancer cells by stimulating the secretion of CXCL16." (PMID 33924999, 2021). "Furthermore, CXCL16 promotes the development of gastric cancer by activating the ADAM10-dependent CXCL16/CXCR6 axis." (PMID 37272931, 2023). "Likewise, CXCR6 expression in gastric cancer HGC-27 cells is positively associated with the proliferation of cancer cells, as well as CXCL16 expression in osteosarcoma U2OS and SaOS2 cells, and CXCR6 in osteosarcoma MG-63 cells." (PMID 33800554, 2021). "Future research could focus on developing inhibitors against CXCL16 or CXCR6 and evaluating their efficacy in gastric cancer treatment." (PMID 40452847, 2025). "Evidence was accumulated that chemokines and their receptors had a strong relationship with poor clinical outcomes in different tumor progression, such as that CCR6 and CXCL16/CXCR6 were involved in regulation proliferation, metastasis, and EMT in ESCC and Gastric cancer tumorigenesis." (PMID 34943853, 2021). "In gastric cancer CXCL16 expression does not differ from adjacent non-cancerous tissues." (PMID 33800554, 2021).